FUNDC1 (FUN14 domain containing 1)
Diseases named in the same sentence as FUNDC1 in open-access papers (continued):
Sharing a sentence is not in itself a finding about the gene and the disease.
kidney disease (1 paper, 2024). "This article will review the multifaceted role of mitochondrial autophagy receptor FUNDC1 in mitochondrial events and renal diseases, in order to provide a theoretical basis and new perspective for the research and treatment of renal diseases." (PMID 39445333, 2024). "In the aspect of kidney disease, the abnormal function of FUNDC1 is closely related to the occurrence and development of many diseases." (PMID 39445333, 2024). "In short, FUNDC1 is a key mitochondrial autophagy regulator, and its role in maintaining mitochondrial function and kidney disease is worthy of further exploration." (PMID 39445333, 2024). "This article focuses on the role of the mitophagy receptor FUNDC1 in maintaining mitochondrial function and kidney disease." (PMID 39445333, 2024). "Mitochondrial autophagy receptor FUNDC1 plays a key role in maintaining mitochondrial function and kidney disease." (PMID 39445333, 2024). "In the context of kidney disease, the imbalance of mitochondrial autophagy mediated by FUNDC1 is closely related to the development of AKI, CRS, DN, CKD, RF, and renal anemia." (PMID 39445333, 2024). "Future research needs to further explore the molecular mechanism of FUNDC1 and its application in the treatment of renal diseases." (PMID 39445333, 2024). "In recent years, studies have found that “intestinal flora metabolism-FUNDC1-mediated mitochondrial autophagy” pathway may be a new way to improve inflammatory damage in renal disease." (PMID 39445333, 2024). "The phosphorylation of FUNDC1 may affect the activity of mitochondrial autophagy, which in turn affects the inflammatory response of kidney disease." (PMID 39445333, 2024). "Recent studies have revealed the close relationship between FUNDC1 and kidney disease, and pointed out that mitochondrial dysfunction can be improved by regulating the activity of FUNDC1, which provides a new molecular target for the treatment of kidney disease." (PMID 39445333, 2024). "In the context of kidney disease, FUNDC1-mediated mitochondrial autophagy may play a key role in cell response to injury and recovery." (PMID 39445333, 2024). "Therefore, in-depth study of the regulatory mechanism and function of FUNDC1 is of great significance for understanding the pathogenesis of renal disease and developing new treatment strategies." (PMID 39445333, 2024). "Second, the effects of FUNDC1 may be different in different types of kidney disease." (PMID 39445333, 2024). "By regulating the abundance of intestinal flora to activate FUNDC1-mediated mitochondrial autophagy and inhibit NLRP3-mediated inflammation, we can adjust the homeostasis of intracellular environment and treat renal disease." (PMID 39445333, 2024). "This article reviews the latest research progress on the role of mitochondrial autophagy receptor FUN14 domain containing 1 (FUNDC1) in mitochondrial events and kidney disease." (PMID 39445333, 2024).
myopathy (1 paper, 2025). A disease of the muscle in which the muscle fibers do not function properly. "The expression of voltage dependent anion channel 1 (VDAC1), FUN14 domain containing 1 (FUNDC1), and translocase of outer mitochondrial membrane 20 (TOMM20) genes was not affected neither by the WB myopathy nor by the hypoxia exposure of primary myoblasts." (PMID 40034536, 2025).
neurodegenerative disease (1 paper, 2025). A disorder of the central nervous system characterized by gradual and progressive loss of neural tissue and neurologic function. "Studies have shown that in neurodegenerative diseases such as AD, FUNDC1 can bi-directionally regulate mitochondrial autophagy and thus play a corresponding role." (PMID 40421101, 2025). "In addition to AD, the role of FUNDC1 in other neurodegenerative diseases, especially in PD and ALS, has likewise attracted widespread attention, and its functional regulation in these diseases may provide potential targets for new therapeutic strategies." (PMID 40421101, 2025).
FUNDC1 also shares sentences with these, for which no sentence is quoted: prostate adenocarcinoma (3 papers); chronic kidney disease (2); Diabetic Nephropathy (2); lung adenocarcinoma (2); acute myocardial infarction (1); acute respiratory distress syndrome (1); amyotrophic lateral sclerosis (1); breast adenocarcinoma (1); breast invasive carcinoma (1); Cachexia (1); cholangiocarcinoma (1); colon adenocarcinoma (1); energy metabolism disorders (1); head and neck squamous cell carcinoma (1); kidney chromophobe (1); liver diseases (1); Lung Injury (1); lymphoma (1); metabolic syndrome (1); neurological disorders (1); Pan (1); prostate carcinoma (1); pulmonary fibrosis (1); pulmonary hypertension (1); rectum adenocarcinoma (1); Ureteral obstruction (1); uterine corpus endometrial carcinoma (1).